HMOX1 (heme oxygenase 1)
Diseases named in the same sentence as HMOX1 in open-access papers (continued):
Sharing a sentence is not in itself a finding about the gene and the disease.
COVID-19 (73 papers, 2020 to 2026). A disease caused by infection with severe acute respiratory syndrome coronavirus 2. "Another gene related to COVID-19 pathogenesis is HMOX1, which encodes heme oxygenase one (HO-1), a protein involved in heme catabolism with anti-inflammatory effects." (PMID 37809329, 2023). "If the binding surface between HMOX1 and ORF3a is determined, will gene variants that disrupt this interaction alter COVID-19 inflammatory severity?" (PMID 32899231, 2020). "The study also investigated whether there is a correlation between HMOX-1 promoter gene polymorphism, serum HMOX-1 enzyme level and several inflammatory and clinical markers in COVID-19 patients." (PMID 38129860, 2023). "The respective APNet bipartite graph contained a large cluster (IL10RA, ACTN4, ITGB2, IL2RB, BIRC2, ITGAM, HMOX1, TIMP1) linked with established COVID-19 inflammatory and immune signalling cascades." (PMID 39921901, 2025). "Taken together, the decrease in the expression of CDH1, ACE2, and HMOX1 genes suggests that HBECs exposed to serum from the most severe COVID-19 patients (WHO-CPS = 9) acquire a dysfunctional and/or infected phenotype." (PMID 38494528, 2024). "A novel Single nucleotide polymorphism (SNP) (A > G) - rs13057211 in the GT(n) region of HMOX-1 promoter gene was found in 40 (61.5%) COVID-19 patients out of the studied 65 patients." (PMID 38129860, 2023). "A di-nucleotide repeat of GT in the promoter of the heme oxygenase 1 gene (HMOX1) has been suggested to participate in the COVID-19-induced cytokine storm by affecting the transcription of HO-1 to reactive oxygen species." (PMID 36009328, 2022). "Expression of genes like HIF1A, HMOX1, and high mobility group box 1 (HMBG1) was associated with myocarditis in COVID-19 patients." (PMID 36009328, 2022). "By taking the intersection of COVID-19/HCC genes and vitamin D-associated targets, we obtained seven overlapping genes (HMOX1, MB, TLR4, ALB, TTR, ACTA1 and RBP4) of vitamin D against COVID-19/HCC." (PMID 36275701, 2022). "Next, we further analyzed the possible binding of vitamin D with the seven COVID-19/HCC targets (HMOX1, MB, TLR4, ALB, TTR, ACTA1 and RBP4) identified previously and found that vitamin D only binds to MB and RBP4." (PMID 36275701, 2022). "The Nrf2 pathway is reported as a promising therapeutic target against COVID-19, as it and its antioxidant enzyme heme oxygenase-1 (HO-1) inhibit inflammatory regulatory pathways such as NF-κB." (PMID 35562935, 2022). "The new point of this study is that total bilirubin level, a marker of heme oxygenase-1 enzyme activity, can predict heart damage in patients with COVID-19." (PMID 34928467, 2021). "Transcriptome analysis of severe COVID-19 patients has shown that NRF2 dependant genes are suppressed including Heme Oxygenase 1 (HMOX1) and NAD(P)H Quinone Dehydrogenase 1 (NqO1)." (PMID 34240083, 2021). "This study aimed to investigate the predictive value of the total bilirubin level, a marker of heme oxygenase-1 enzyme activity, in determining myocarditis in patients with COVID-19." (PMID 34928467, 2021). "We also throw light on the benefits of naturally occurring compounds and potential mechanisms that can be elucidated to understand the molecular targets of the HMOX1 pathway and other pathways that are altered in COVID-19 patients." (PMID 32899231, 2020). "Here, we review the potential of modulating the HMOX1-ORF3a nexus to regulate the innate immune response for therapeutic benefits in COVID-19 patients." (PMID 32899231, 2020). "Given the central role of inflammation in severe COVID-19 cases, this binding interaction is promising because HMOX-1 activity reduces inflammation and tissue damage via the NLRP3 pathway." (PMID 32899231, 2020). "The HMOX1 pathway can inhibit platelet aggregation and has anti-thrombotic and anti-inflammatory properties, all of which are compromised during critical medical conditions in COVID-19 patients." (PMID 38494528, 2024).
COVID-19 (continued). "In addition to the HMGB1 protein, the recent literature indicates that serum levels of heme oxygenase-1 (HO-1) should also be determined in COVID-19 patients because it can prevent the consequences of hemolysis." (PMID 37685970, 2023). "In this retrospective cross-sectional study, we found that serum concentrations of high-mobility group box 1 (HMGB1) and heme oxygenase-1 (HO-1), at the time of hospital admission, could be useful biomarkers for COVID-19 management." (PMID 37685970, 2023). "Through unbiased KEGG pathway analysis of DEGs between Fga−/− and WT plasma-stimulated microglia, we identified the 12 top pathways induced by fibrinogen, including ROS (for example, Hmox1, Cox7a2, Slc25a5), COVID-19 (for example, Ccl12, Rps8, Rpl35) and AD (for example, Atp5e, Psmd2, Tubb5)." (PMID 37291385, 2023). "Thus, drugs targeting HMOX1-ORF3a binding or enhancing expression of HMOX1 gene can be suggested as new alternatives for COVID-19 treatment." (PMID 35831333, 2022). "As a matter of fact, the HO-1 gene expression, HMOX1, has been reported in COVID-19." (PMID 36001619, 2022). "Therefore, the purpose of this study was to investigate the relationship between total bilirubin levels, a marker of heme oxygenase-1 enzyme activity, and myocarditis in COVID-19." (PMID 34928467, 2021). "There are a number of approaches that could be used to investigate the role of HMOX1 and ORF3a in COVID-19 pathogenesis." (PMID 32899231, 2020). "Although the ultimate goal of developing drugs that upregulate HMOX1 or inhibit its binding to viral ORF3a is to treat severe disease, early candidates could be used as tools to determine the role of the HMOX1 pathway in COVID-19 inflammatory dysregulation." (PMID 32899231, 2020). "The HMOX1 pathway can inhibit platelet aggregation, and can have anti-thrombotic and anti-inflammatory properties, amongst others, all of which are critical medical conditions observed in COVID-19 patients." (PMID 32899231, 2020). "While much effort has been focused on inhibiting the binding of the spike protein to the human ACE2 receptor, we propose that a similar effort should be made in developing ORF3a-HMOX1 inhibitors, if only as a tool to better understand the role of this interaction in COVID-19." (PMID 32899231, 2020). "HMOX1 expression might be a prognostic biomarker for COVID-19 disease." (PMID 35831333, 2022). "Serum from patients with severe COVID-19 significantly upregulated genes involved in the cellular antioxidant response in HUVEC, including NFE2L2, HMOX1, SOD1, CAT, GPX1, and GSR." (PMID 41583455, 2025). "Innate Fe-Redox regulators such as lactoferrin (LF), heme oxygenase-1 (HO-1), erythropoietin (EPO), and hepcidin (HEP) serve as first innate barriers against free radical damage and hyper-immune responses during COVID-19 and PASC27." (PMID 38555403, 2024). "It has been reported that HO-1 is strongly and exclusively induced in M2, and enhanced HO-1 gene expression, HMOX1, in COVID-19." (PMID 36001619, 2022). "Heme metabolism may be important clinically and therapeutically, since activating heme-oxygenase-1 through hemin suppressed SARS-CoV-2 replication in vitro, thus heme metabolism activation could potentially be another avenue for COVID-19 therapeutics." (PMID 37090709, 2023). "Moreover, we identified seven possible pharmacological targets of vitamin D against COVID-19/HCC, including HMOX1, MB, TLR4, ALB, TTR, ACTA1 and RBP4." (PMID 36275701, 2022). "This difference may be attributed to the fact that they compared HMOX-1 mRNA level (not the serum level of HMOX-1) between heathy volunteers and severely ill COVID-19 patients." (PMID 38129860, 2023). "Moreover, following SARS-CoV-2 infection, both mitochondrial superoxide dismutase (SOD2) and heme oxygenase-1 (HO-1) were found to be altered, but their involvement in the pathogenesis of COVID-19 is not clear." (PMID 35159254, 2022).
COVID-19 (continued). "Further, we identified seven overlapping genes of vitamin D against HCC and COVID-19 using the network pharmacology approach, and the anti-COVID-19/HCC effects of vitamin D may be modulated by these molecules or genes, including HMOX1, MB, TLR4, ALB, TTR, ACTA1 and RBP4." (PMID 36275701, 2022).
pancreatic cancer (71 papers, 2008 to 2025). "Based on proteomic evidence, we are the first to suggest that FX activates the AMPK/Nrf2/HMOX1 pathway, as this axis has previously been implicated in ferroptosis induction by erastin and vitamin C agents in pancreatic cancer cells." (PMID 40137309, 2025). "Recent studies have shown that vitamin C enhances the susceptibility of pancreatic cancer cells to erastin-induced ferroptosis through the activation of the AMPK/Nrf2/HMOX1 pathway." (PMID 40137309, 2025). "Our novel findings suggest that CBC treatment induces HMOX1-dependent ferroptosis in pancreatic cancer cells." (PMID 40790027, 2025). "We evaluated the relationship between KLF5, ZEB1, and HMOX1 expression in tissues from pancreatic cancer patients." (PMID 39827156, 2025). "Heme oxygenase (HO-1 or the HMOX1 gene in humans) is in part regulated by NRF2, and macrophages expressing HO-1 in pancreatic tumors can promote immunotolerance." (PMID 39337472, 2024). "It has been reported that HMOX1 upregulation enhances the growth and angiogenesis of pancreatic cancer during oxidative stress and HMOX1 downregulation improves responsiveness of PDAC cells to chemotherapy." (PMID 37653101, 2023). "Inhibiting Heme oxygenase 1 with zinc protoporfiphyrin and tin protoporphyrin IX increased both ROS production and apoptosis, thus sensitizing pancreatic cancer cells to gemcitabine." (PMID 34885243, 2021). "On the other hand, HMOX1 expression has been found to interfere with anticancer treatments against pancreatic cancer." (PMID 30057678, 2018). "Together with these HMOX1-inducing effects, statins simultaneously inhibit pancreatic cancer cell proliferation." (PMID 27175805, 2016). "Nevertheless, our data from HMOX1/2 silencing support pro-carcinogenic role of HMOX in pancreatic cancer, consistent with previous clinical observation." (PMID 27175805, 2016). "This might really have relevance to their anticancer effects, since HMOX1 expression has been reported to prevent the responsiveness of pancreatic cancer to cytostatic therapy." (PMID 30057678, 2018). "However, the upregulation of HMOX1 in pancreatic cancer cells was previously connected to worsened treatment outcome." (PMID 27175805, 2016). "Moreover, pancreatic cancer cells were shown to overexpress HMOX1 compared to normal pancreatic tissue." (PMID 27175805, 2016). "Irradiation induced HMOX1 expression on pancreatic cancer cells." (PMID 25182732, 2014). "Thus, the combination of activation of the KLF5/ZEB1/HMOX1 axis and oxaliplatin may provide a potential therapeutic strategy for pancreatic cancer." (PMID 39827156, 2025). "We further performed qRT-PCR on five selected ferroptosis-related genes (HMOX1, CHAC1, SLC3A2, SLC7A11, and FTH1) in pancreatic cancer cells after 12 and 24 h of CBC treatment." (PMID 40790027, 2025). "When RPL10 was knocked-down in PANC-1 and MIA PaCa-2 cells, the expression of OSGIN1 indeed markedly increased, whereas HMOX1 showed little change in both cells, indicating that RPL10 is possible to regulate ROS level in pancreatic cancer cells." (PMID 30172100, 2018). "To further resolve if HMOX is involved in anti-proliferative effects of statins on human pancreatic cancer, we silenced HMOX1 and HMOX2 in pancreatic cancer cells with esiRNA and assessed cell proliferation after 48 h of exposure to cerivastatin and hemin." (PMID 27175805, 2016). "To verify that ZEB1 regulated HMOX1, we established stable ZEB1-silenced pancreatic cancer cells." (PMID 39827156, 2025). "Consistently, HMOX1 protein levels were significantly elevated following CBC treatment, as shown through western blot analysis, emphasizing that it acts as a key regulator of CBC ferroptosis in pancreatic cancer cells." (PMID 40790027, 2025).
colorectal cancer (69 papers, 2014 to 2026). A primary or metastatic malignant neoplasm that affects the colon or rectum. "In another field, HMOX1 has also been associated with colorectal cancer, being suggested as a novel target for cancer therapy." (PMID 30258436, 2018). "HMOX1 has been associated with different types of cancer, including prostate cancer, bladder cancer, skin cancer, and colorectal cancer (CRC)." (PMID 30258436, 2018). "Interaction between dietary factors and HMOX1 A-413T (rs2071746) in relation to colorectal cancer risk." (PMID 25574604, 2015). "Interaction between NSAID use and HMOX1 A-413T (rs2071746) in relation to colorectal cancer risk." (PMID 25574604, 2015). "A study has shown that the upregulated Nrf2-dependent transcription of heme oxygenase-1 (HO-1) promotes ferroptosis in colorectal cancer (CRC) cells." (PMID 40083691, 2025). "Tagitinin C promotes ferroptosis in colorectal cancer cells by inducing ER stress to activate Nrf2/HMOX1 signaling." (PMID 38503948, 2025). "Both KAE and cisplatin led to extensive reduction in the levels of Autotaxin, Carbonic Anhydrase IX, cathepsins, MMP-3, u-Plasminogen Activator/Urokinase, and HMOX1 in colorectal carcinoma cultures." (PMID 41515404, 2025). "In our research, the treatment of colorectal cancer cells with OMe-Ph-Elemene led to the modulation of several crucial proteins associated with oxidative stress and cell apoptosis, including TRIAP1, HMOX1, and CISD3." (PMID 39765827, 2024). "What’s more, Zn2+ can increase the expression of heme oxygenase-1 (HO-1) mRNA and protein in colorectal cancer cell lines, which can be inhibited by the iron-binding agent deferoxamine (DFO)." (PMID 36033459, 2022). "Increased circulating carboxyhemoglobin (COHb) levels have been observed in patients with colorectal cancer through upregulation of heme oxygenase-1 (HO-1)." (PMID 35448437, 2022). "The mRNA levels of Hmox1, Nrf2, Keap1, and Bach1 in the tumor and normal tissues of 84 subjects with colorectal cancer (CRC) were determined by real-time polymerase chain reaction." (PMID 27999449, 2016). "Moreover, cetuximab was found to enhance RSL3-induced ferroptosis in colorectal cancer cells by inhibiting the p38/NRF2/HMOX1 signaling pathway." (PMID 39857803, 2025). "Heme oxygenase-1 (HO-1) exerts anti-tumor activity in prostate and colorectal cancers." (PMID 30736789, 2019). "Genes, such as HMOX1 and VEGFB, are important for the invasion of various cancer cells, such as bladder cancer and colorectal cancer, but these genes may be associated with the invasion of BRCA cells." (PMID 31311202, 2019). "Incidence rate ratios (IRR) for colorectal cancer in relation to HMOX1 A-413T (rs2071746)." (PMID 25574604, 2015). "IRR for colorectal cancer for tertiles of intake of dietary factors for HMOX1 A-413T (rs2071746)." (PMID 25574604, 2015). "Heme oxygenase-1 (HO-1) is upregulated in colorectal carcinoma (CRC) cells." (PMID 26087182, 2015). "For instance, β-elemene and cetuximab upregulate heme oxygenase 1 (HO-1) and transferrin to induce ferroptosis in KRAS mutant colorectal cancer." (PMID 37408372, 2023). "Furthermore, in colorectal cancer, curcumin can modulate gene expression of HSPA5, SEC61B, G6PD, HMOX1, and PDE3B, affecting essential pathways like DNA replication or the cell cycle." (PMID 31744117, 2019). "Likewise, Tagitinin C, another natural compound, induces ferroptosis in colorectal cancer cells through the PERK–NRF2–HMOX1 signaling pathway, and again the significant overexpression of HMOX1 led to the increase in the LIP, which promoted lipid peroxidation and ferroptosis." (PMID 36899871, 2023).
colorectal cancer (continued). "Interestingly, the analysis revealed that Hmox1 exhibited remarkable specificity for myeloid cells, predominantly expressed within this cell population, whereas it exhibited minimal to negligible expression in other cell types within the TME of both breast and colorectal cancers." (PMID 37958903, 2023).